NT5E (5'-nucleotidase ecto)
Description:
Catalyzes the hydrolysis of nucleotide monophosphates, releasing inorganic phosphate and the corresponding nucleoside, with AMP being the preferred substrate. Shows a preference for ribonucleotide monophosphates over their equivalent deoxyribose forms. Other substrates include IMP, UMP, GMP, CMP, dAMP, dCMP, dTMP, NAD and NMN.
Synonyms: CD73; NT5; NTE; eN; eNT; CALJA; E5NT; NT
Tractability: Small molecule: a structure with a bound ligand is known; a high-quality ligand is known; it belongs to a druggable protein family. Antibody: a drug acting on it is in phase 2 or 3 trials; UniProt places it where antibodies can reach, with high confidence; its Gene Ontology location is reachable by antibodies, with high confidence; UniProt predicts a signal peptide or a membrane-spanning region; the Human Protein Atlas places it where antibodies can reach. PROTAC: ubiquitination databases record sites on it; its protein half-life has been measured; a small molecule that binds it is known.
Target class: Enzyme; Phosphatase
Chemical probes: QUEMLICLUSTAT (high quality)
Gene: Protein-coding gene on chromosome 6 (85,449,584 to 85,495,791, forward strand). Ensembl gene ENSG00000135318.
Subcellular location: Cell membrane
Subcellular location (Human Protein Atlas): Plasma membrane; Cytosol; Nucleoplasm
Pathways (Reactome):
Metabolism: Nicotinate metabolism; Purine catabolism; Pyrimidine catabolism
Disease: Purinergic signaling in leishmaniasis infection
Gene Ontology:
Molecular function: 5'-deoxynucleotidase activity; 5'-nucleotidase activity; identical protein binding; protein binding; zinc ion binding; hydrolase activity; hydrolase activity, acting on ester bonds; metal ion binding; nucleotide binding
Biological process: ATP metabolic process; biomineral tissue development; leukocyte cell-cell adhesion; response to ATP; AMP catabolic process; ADP catabolic process; calcium ion homeostasis; nucleotide catabolic process
Cellular component: cell surface; extracellular exosome; membrane; plasma membrane; external side of plasma membrane
Genetic constraint (gnomAD): Loss-of-function variants: 52 observed, 52.23 expected, observed/expected ratio (o/e) 1, 90% interval 0.8 to 1.25. The upper end of that interval is the gene's LOEUF score, 1.25, which puts it in group 5 of 6, group 1 being the genes least tolerant of losing a copy. Missense variants: 677 observed, 724.78 expected, observed/expected ratio (o/e) 0.93, 90% interval 0.88 to 1. Synonymous variants: 264 observed, 279.99 expected, observed/expected ratio (o/e) 0.94, 90% interval 0.85 to 1.04.
Homologues: Orthologues: chimpanzee NT5E (99% identical), macaque NT5E (99% identical), dog NT5E (91% identical), pig NT5E (91% identical), rabbit NT5E (89% identical), rat Nt5e (88% identical), mouse Nt5e (87% identical), guinea pig NT5E (86% identical), tropical clawed frog nt5e (65% identical), zebrafish nt5e (62% identical), Drosophila melanogaster veil (39% identical), Drosophila melanogaster NT5E-2 (39% identical), and 2 more.
Diseases named in the same sentence as NT5E in open-access papers:
NT5E is named in the same sentence as 401 diseases in open-access papers, as found by Europe PMC text mining. Sharing a sentence is not in itself a finding about the gene and the disease. The quoted sentences say what the papers report.
breast cancer (174 papers, 1991 to 2025). A primary or metastatic malignant neoplasm involving the breast. "In summary, this work demonstrates that GRHL2, a key epithelial transcriptional regulator, can regulate extracellular adenosine levels produced by breast cancer cells through suppression of the gene encoding the NT5E/CD73 ecto-enzyme." (PMID 38706844, 2024). "In accordance, high NT5E/CD73 expression level is significantly associated with worse prognosis for breast cancer patients." (PMID 37409119, 2023). "Recent findings have highlighted NT5E’s role in promoting the growth and metastasis of human breast cancer cells." (PMID 40612859, 2025). "These clinical characteristics imply a possible oncogenic role for NT5E in breast cancer, especially in TNBC." (PMID 40612859, 2025). "Taken together, in agreement with the findings in the MCF-7 conditional KO model, these findings indicated that NT5E/CD73 is negatively correlated with GRHL2 in human breast cancer cell lines and breast cancer patients." (PMID 38706844, 2024). "GRHL2 binds an intronic NT5E sequence and is negatively correlated with NT5E/CD73 in breast cancer cell lines and patients." (PMID 38706844, 2024). "Our finding that NT5E/CD73 is inversely correlated with GRHL2 in breast cancer cell lines and in patient tumors or tumor areas suggests the negative regulation of CD73 by GRHL2 in breast cancer is common." (PMID 38706844, 2024). "To address the relation between CD73 expression and CD8 T cell recruitment in breast cancer, we examined the association NT5E mRNA levels and CD8 T cell infiltration using the TIMER 2.0 patient dataset." (PMID 38706844, 2024). "This study firstly found that reversible senescence contributed to LAP(lapatinib) resistance in HER2+ breast cancer and identified ecto‐5′‐nucleotidase (NT5E) as a marker of reversible senescence in HER2+ breast cancer." (PMID 37792675, 2023). "Ample evidence has shown that NT5E is overexpressed in many cancers, such as breast cancer, pancreatic ductal adenocarcinoma, and non‐small cell lung cancer." (PMID 37792675, 2023). "Then, we identified ecto‐5′‐nucleotidase (NT5E) as a marker of reversible senescence in HER2+ breast cancer." (PMID 37792675, 2023). "PANX1 expression was also positively correlated with tumor-associated neutrophil (TAN) infiltration in breast cancer TME and TANs highly expressed ENTPD1 (CD39)/NT5E (CD73)." (PMID 35884429, 2022). "Functionally, PCBP2 promoted the carcinogenesis and metastasis of breast cancer by directly regulating the expression of ubiquitin recognition factor in ER-associated degradation 1 (UFD1) and 5’-nucleotidase ecto (NT5E) via binding to their 3’UTRs." (PMID 36059653, 2022). "Methods and Results: Here, by studying a large collection of human samples, we highlight the key function of CD73/NT5E in CAF-S1-mediated immunosuppression in breast cancer." (PMID 34884993, 2021). "More detailed analyses of the tumor microenvironment are needed to understand the mechanisms involved in the regulation of the NT5E gene methylation and CD73 expression in breast cancer." (PMID 33198064, 2020). "A single previous study has investigated the NT5E gene methylation in breast cancer, but to our knowledge, this is the first report of CD73 methylation analysis in fresh frozen human breast cancer tissue and normal human breast tissues." (PMID 33198064, 2020). "Leth-Larsen and colleagues also showed that intense NT5E/CD73 IHC staining was more common for breast cancer patients with relapse and lymph node metastases." (PMID 29514610, 2018). "The expression level of CD73/NT5E in breast cancer versus matched normal tissue." (PMID 29514610, 2018).
breast cancer (continued). "In addition, NT5E expression and its generation of adenosine may relate to breast cancer progression and increased expression of CD73 in ER-negative cells may serve as a novel marker for more aggressive breast carcinoma." (PMID 24310606, 2014). "ENTPD1, NT5E, and ADORA3 showed higher expression in bone metastases than in primary breast cancers,top, GSE47561." (PMID 36186774, 2022). "In primary ER+ breast cancer, high levels of the triplet ENTPD1/NT5E/ADORA3 expression signature was correlated with lower overall, distant metastasis-free, and progression-free survival." (PMID 36186774, 2022). "We developed a novel GRG signature of six GRGs, including CACNA1H, CHPF, IRS2, NT5E, SDC1 and ATP6AP1, to predict survival and guide individual therapy in breast cancer." (PMID 36277284, 2022). "CD73 expression is also impacted by NT5E promoter methylation, described for both melanoma and breast cancer." (PMID 32351498, 2020). "NT5E is a 70 kDa glycosylated protein anchored to the extracellular surface of the plasma membrane by a glycosylphosphatidylinositol (GPI) anchor and is overexpressed in various tumors, including breast cancer." (PMID 40612859, 2025). "Having established an inverse correlation between GRHL2 and NT5E/CD73, we asked whether the NT5E gene could be subject to direct transcriptional regulation by GRHL2 in breast cancer." (PMID 38706844, 2024). "The co-regulation analysis revealed a significant negative relation between GRHL2 and NT5E mRNAs in breast cancer patient tumors with a Spearman value of −0.32 (p < 0.001)." (PMID 38706844, 2024). "The RNA-seq data of surgical breast cancer specimens (basal-like PANX1 high: n = 6; basal-like PANX1 low: n = 6; Luminal subtype: n = 3) suggested a higher expression of ENTPD1 and NT5E in the basal-like PANX1-high group compared to basal-like PANX1-low and Luminal group (p < 0.05)." (PMID 35884429, 2022). "In human breast cancer, increased CD73 expression is inversely correlated with a lack of methylation of NT5E CpG island and is associated with less favorable patient outcomes." (PMID 33430239, 2021). "Despite the significance of CD73 in immuno-oncology, the roles of the NT5E gene methylation in breast cancer have not been well-defined yet." (PMID 33198064, 2020). "The ENTPD1/NT5E/ADORA3 expression signature was not correlated with either outcome in ER–, HER2-enriched, or basal breast cancers, which do not share the same metastatic behavior, nor were signatures combining expression of the ectonucleotidases with any of the other aADO receptors in ER+ tumors." (PMID 36186774, 2022).
melanoma (119 papers, 2012 to 2026). A malignant, usually aggressive tumor composed of atypical, neoplastic melanocytes. "In malignant melanoma expression of CD73 is epigenetically regulated and methylation in the NT5E (CD73) CpG island is associated with high risk of metastasis to brain and visceral sites." (PMID 29202855, 2017). "In the present study, we show that NT5E (CD73) is subject to methylation-dependent transcriptional silencing in melanoma, with potential clinical and therapeutic implications." (PMID 22454080, 2012). "The expression level of CD73/NT5E in melanoma versus matched normal tissue." (PMID 29514610, 2018). "Primary melanomas that do not epigenetically downregulate the transcription of the NT5E gene (that encodes CD73) were found to metastasize more often." (PMID 29928476, 2018). "Inhibition of NT5E may have therapeutic potential in melanoma, particularly in patients with more aggressive disease metastatic to viscera or the brain." (PMID 22454080, 2012). "Here, we report that expression of NT5E (CD73) is regulated epigenetically in malignant melanoma." (PMID 22454080, 2012). "However, it has been previously shown that NT5E mRNA is upregulated during differentiation of melanoma cell lines." (PMID 22454080, 2012). "A bifunctional PD-L1/CD73(NT5E) small-molecule inhibitor was developed, exhibiting high PD-L1 and NT5E inhibitory activity in a melanoma model." (PMID 40612859, 2025). "A number of identified molecules including TNFRSF13B, LAG3, NRP1, ENTPD1, NT5E, CCL21, and CCR7 can serve as future therapeutic targets in melanoma treatment." (PMID 34159752, 2021). "A number of identified molecules, including TNFRSF13B, LAG3, NRP1, ENTPD1, NT5E, CCL21, and CCR7, can serve as future therapeutic targets in the treatment of melanoma." (PMID 34159752, 2021). "MICA, NT5E/CD73 and tactile/CD96 showed statistically significant increase in melanoma patients vs. HDs." (PMID 30761123, 2019). "HD and melanoma patient sera were tested for immunosuppressive factors MICA, NT5E/CD73 and tactile/CD96, as well as perforin, which is released by cytotoxic NK and T cells and is a surrogate biomarker for in vivo cytolytic activity of these effectors." (PMID 30761123, 2019). "Finally, melanoma-derived exosomes were shown to contain a number of immunosuppressive proteins, such as galectins (LGALS1 and LGALS3) and 5′-nucleotidase (NT5E)." (PMID 31086060, 2019). "Two more of these target genes, NT5E and PNP, are candidate biomarkers for malignant melanoma." (PMID 26472186, 2015).
glioma (67 papers, 2004 to 2025). A benign or malignant brain and spinal cord tumor that arises from glial cells (astrocytes, oligodendrocytes, ependymal cells). "MicroRNA‐30a inhibits self‐renewal of glioma stem cells through blocking NT5E‐dependent Akt signaling." (PMID 36303447, 2022). "To date, several circRNAs have been reported to play crucial roles in gliomas, such as circ-SMARCA5, circ-MMP9, circ-NT5E, circ-TTBK2, and circ-LINC-PINT." (PMID 31905344, 2020).
ovarian carcinoma (66 papers, 2014 to 2025). A malignant neoplasm originating from the surface ovarian epithelium. "Similarly, our observations that single gene knockouts of ALDOB, ADH1B, NEU1, and NT5E block the metabolic alterations during both transitions concur with previous studies that show suppression of ovarian cancer growth upon silencing these genes." (PMID 37876796, 2023). "The expression level of CD73/NT5E in ovarian cancer versus matched normal tissue." (PMID 29514610, 2018).
colorectal cancer (62 papers, 2014 to 2026). A primary or metastatic malignant neoplasm that affects the colon or rectum. "The expression level of CD73/NT5E in colorectal cancer versus matched normal tissue." (PMID 29514610, 2018). "This confirmed that NT5E/CD73 is a component of EVs derived from colorectal cancer cells." (PMID 25469109, 2014).
glioblastoma (62 papers, 2012 to 2026). The most malignant astrocytic tumor (WHO grade IV). "CD73, a cell-surface protein encoded by the gene NT5E, is overexpressed in glioblastoma (GBM), where it contributes to the tumor’s pathophysiology via the generation of immunosuppressive adenosine." (PMID 31547570, 2019). "Glioblastoma expresses the immune markers in CD73/NT5E (5′ nucleotidase, ecto), and CKLF." (PMID 23251904, 2012).
lung carcinoma (58 papers, 2017 to 2026). "The expression level of CD73/NT5E in lung cancer versus matched normal tissue." (PMID 29514610, 2018).
pancreatic cancer (52 papers, 2014 to 2026). "The Cancer Genome Atlas (TCGA) data analysis revealed that NT5E gene expression was strongly correlated with CD44 and ROCK1/ROCK2 gene expressions in pancreatic tumors, suggesting a link between CD73 and loss of epithelial features." (PMID 37851808, 2023). "We observed that NT5E expression was associated with several gene sets linked to amoeboid migration and pancreatic cancer progression, such as transforming growth factor–β (TGF-β), KRAS, WNT, nuclear factor κB (NF-κB) and IL-6/JAK/STAT3 signaling, hypoxia, or EMT." (PMID 37851808, 2023). "The membrane protein CD73/NT5E was initially the focus in defining pancreatic cancer specific markers." (PMID 25469109, 2014). "Moreover, a phase I clinical trial using a small-molecule NT5E inhibitor in patients with pancreatic cancer is ongoing; early results are promising, with an overall response rate of 41%." (PMID 39911580, 2024). "The expression level of CD73/NT5E in pancreatic cancer versus matched normal tissue." (PMID 29514610, 2018). "Additionally, the expression of NT5E/CD73 is upregulated in pancreatic cancer on transcriptional level." (PMID 25469109, 2014). "The choice of NT5E/CD73 as a potential cancer biomarker was supported by previous findings that three out of five pancreatic cancer cell lines released more peptides of NT5E/CD73 in the secretomes, compared to normal epithelial model cells HPDE (Klein-Scory, S. unpublished data)." (PMID 25469109, 2014). "Our integrative single-cell and bulk-RNA workflow identifies ANLN, NT5E, and CTSV as novel prognostic biomarkers in pancreatic cancer and highlights a pro-tumorigenic interaction between malignant ductal cells and macrophages." (PMID 40666516, 2025). "Moreover, LOX was 1 out of only 5 probe sets that overlapped between the Glasgow cohort and the Collisson signatures of poor prognosis in pancreatic cancer (the others being S100A2, TWIST, NT5E and PAPPA)." (PMID 26077591, 2015). "Although the pancreatic carcinoma cells express and release more NT5E/CD73 than the model cell line HPDE, the specificity of this protein for carcinoma cells is limited: for example, the immortalized human pancreatic stellate cells hPSC (and mesenchymal cells) release this protein." (PMID 25469109, 2014).
gastric cancer (41 papers, 2014 to 2026). A primary or metastatic malignant neoplasm involving the stomach. "The immune-stimulator gene NT5E is related to poor survival in gastric cancer, and silencing of NT5E suppresses proliferation, invasion, and migration." (PMID 37779898, 2023). "The expression level of CD73/NT5E in gastric cancer versus matched normal tissue." (PMID 29514610, 2018). "By analyzing the co-expression correlation between CPT1A, IL-8, CXCL5, STC1 and CD44 in stomach cancer tissues through TCGA database, we found that these genes except CXCL5 were positively correlated with CD44 and were positively associated with at least one MSC markers (ENG, THY1, NT5E)." (PMID 37158903, 2023). "The effects of somatic mutations in genes encoding zinc finger proteins (ZNF721 and ZFYVE16), a purine and pyrimidine metabolism protein (NT5E), carbonic anhydrase(CA1), and cyclic nucleotide phosphodiesterase(PDE10A)on the progress of gastric cancer requires further study." (PMID 27270314, 2016).
prostate carcinoma (38 papers, 2013 to 2025). A carcinoma that arises from epithelial cells of the prostate gland. "A 3-gene signature composed of ENTPD1, NT5E, and ADORA3 is associated with a greater chance of bone metastasis in ER+ breast and prostate cancers." (PMID 36186774, 2022). "The expression level of CD73/NT5E in prostate cancer versus matched normal tissue." (PMID 29514610, 2018). "We also analyzed gene expression in metastatic prostate cancer (GSE74685) and found a similar expression pattern, with ENTPD1, NT5E, and ADORA3 upregulation in bone metastases than in other metastases, bottom." (PMID 36186774, 2022). "We showed that expression of a three-gene expression signature comprising ENTPD1, NT5E, and ADORA3 in primary ER+ breast and prostate cancers was correlated with bone metastases." (PMID 36186774, 2022). "The percentages of NT5E+, TNC+, and PDGFRβ+ cells did not significantly vary between stroma adjacent to benign prostate glands and prostate cancer." (PMID 33600062, 2021).
hepatocellular carcinoma (35 papers, 2018 to 2026). A malignant tumor that arises from hepatocytes. "Most recently, an ecto-5′-nucleotidase (NT5E) known as CD73 has been shown to regulate EMT, both in ovarian and hepatocellular carcinoma." (PMID 33187081, 2020). "Moreover, as in hepatoma cells, we found a correlation between ABCC6 and NT5E expression, the ectonucleotidase responsible for the production of adenosine, and we assessed basal level of expression of both genes." (PMID 35645325, 2022).
head and neck squamous cell carcinoma (28 papers, 2016 to 2026). A squamous cell carcinoma that arises from any of the following anatomic sites: lip and oral cavity, nasal cavity, paranasal sinuses, pharynx, larynx, and salivary glands. "It has been reported that miR-422a targeted NT5E/CD73 and promoted loco-regional recurrence in head and neck squamous cell carcinoma." (PMID 28177876, 2017). "Moreover, miR-422a plays a positive role on head and neck squamous cell carcinoma by targeting NT5E/CD73 that promotes loco-regional recurrence, miR-422a were also found to significantly inhibit TMEM45B expression in squamous cell lung cancer." (PMID 29118671, 2017).